INS (insulin)
Diseases named in the same sentence as INS in open-access papers (continued):
Sharing a sentence is not in itself a finding about the gene and the disease.
Glucose intolerance (continued). "Our results revealed that such treatment did not affect body weight and fasting glucose levels and insulin and glucose intolerance (data not shown)." (PMID 26064446, 2015). "Importantly, insulin clearance, an insulin degradation rate, significantly declined from NGT, IGT to T2DM along the progression of glucose intolerance in the mathematical model." (PMID 26623647, 2015). "In addition, Fgf15 deletion results in glucose intolerance, while FGF19 transgenic mice displayed reduced glucose levels and improved insulin sensitivity." (PMID 24567901, 2014). "Low insulin levels and IR are manifested as glucose intolerance: if a starved person consumes glucose, it is not metabolized by the tissues, its blood levels rose and glucose appears in the urine." (PMID 25476900, 2014). "The mechanisms through which excess PTH blunts insulin sensitivity are still uncertain, but medical treatment of hyperparathyroidism in patients with CKD could lead to correction of glucose intolerance." (PMID 24839054, 2014). "By 6 months of age GPER knockouts of both genders were obese, without changes in food intake or locomotor activity, and insulin resistant but only females exhibited glucose intolerance." (PMID 25400333, 2014). "The statin plus high-fat diet Mig-6d/d mice also showed a reduction in the glucose intolerance, but not in fasting insulin concentration or the HOMA IR index, compared with gefitinib-treated mice." (PMID 25486251, 2014). "This matched observation was also supported somewhat in the PANKO-C57 model, as decreased fasting levels of insulin and C-peptide were reported, but this did not have any impact on glucose intolerance as previously reported in the mixed model." (PMID 25217499, 2014). "In both WT and PRLR−/− mice, glucose intolerance and an impairment of insulin sensitivity were observed demonstrating that the absence of PRLR does not impact the weight gain, the food intake, the adipocyte fate/differentiation and metabolic parameters." (PMID 24667351, 2014). "The n0 - STZ and n2 - STZ models are found almost similar with respect to growth, basal plasma glucose, insulin levels, lack of insulin release in response to glucose, in-vivo glucose intolerance and depletion of pancreatic insulin stores." (PMID 24734054, 2014). "Furthermore, EPO transgenic mice display significantly lower levels of blood glucose, insulin and HA1C, and are resistant to high fat diet (HFD)-induced glucose intolerance and insulin resistance." (PMID 23326455, 2013). "Nevertheless, hyperandrogenemia may impair insulin sensitivity in muscle or white adipose tissue, as it does in PCOS patients, leading to the observed glucose intolerance." (PMID 24278193, 2013). "In summary, we report that liver-specific deletion of SH2B1 does not affect hepatic glucose production, systemic insulin sensitivity, and glucose intolerance." (PMID 24358267, 2013). "Consistently, in T2D db/db mice, SR4 ameliorated glucose intolerance and insulin sensitivity (data not shown)." (PMID 24376752, 2013). "It dose-dependently reduced glucose intolerance in ob/ob mice and improved glucose tolerance and increased insulin sensitivity in DIO mice, without consistently affecting plasma lipids." (PMID 23712280, 2013). "Insulin sensitivity and glucose intolerance are not entirely explained by a woman’s hormonal status." (PMID 24206898, 2013). "The alterations of insulin secretion and insulin sensitivity, rather than β-cell mass, were consistent with the development of glucose intolerance." (PMID 23675523, 2013). "Despite of the glucose intolerance and the high levels of plasma triglycerides, total cholesterol and insulin in HFD-fed rats, no changes on SGZ cell proliferation were observed between STD and HFD rats." (PMID 23741384, 2013).
Glucose intolerance (continued). "Lacking similar species-specific algorithms, insulin resistance in the cat or dolphin must be either measured using clamp methodology or inferred when glucose intolerance or reduced insulin responsiveness are detected." (PMID 24348462, 2013). "We observed neither glucose intolerance nor altered whole body insulin sensitivity in Bmal1 null mice." (PMID 23750248, 2013). "In the present study, we found that under basal conditions (CT diet), chronic treatment with a CB receptor agonist induced glucose intolerance without affecting the insulin levels before (fasting) or after an oral glucose load, compared with the CT group." (PMID 23393605, 2013). "We induced glucose intolerance and hampered insulin sensitivity (tested in ipGTT and ipITT, data not shown) by HFD feeding (3 months feeding)." (PMID 23936011, 2013). "In summary, post-prandial serum glucose and insulin fluctuations observed in healthy dolphins and cats would be consistent with mild degree of glucose intolerance if the same changes were found in non-carnivore species." (PMID 24348462, 2013). "The presence of glucose intolerance in HFD mice could involve a reduced ability of adipose and muscle to uptake glucose in response to insulin secreted by the pancreas." (PMID 23951235, 2013). "From this the authors concluded that the glucose intolerance was due to a lack of inhibition of gluconeogenesis following insulin administration." (PMID 23533642, 2013). "Using the same prediabetic mouse model, we consistently found that [Asu1,6]-OXT treatment improved glucose intolerance and lowered fasting blood insulin levels, and both effects were independent of body weight." (PMID 23700406, 2013). "Oral administration of CBX has increased the fasting insulin levels without affecting glucose- intolerance in obese zucker rats." (PMID 23284633, 2012). "The Ucn 3 KO mice have lower plasma insulin and blood glucose concentrations than WT mice, remain sensitive to insulin and do not develop glucose intolerance and liver steatosis with the same frequency of WT mice." (PMID 23316185, 2012). "Glucose intolerance can result from the absence of glucose-stimulated insulin secretion or a decreased action of insulin in the peripheral tissues, or both." (PMID 22816003, 2012). "Glucose intolerance was observed in TCF7L2-knockdown mice compared with control, suggesting that insulin signaling might be perturbed with acute depletion of TCF7L2 in mice." (PMID 23028378, 2012). "On the other hand, 17β-estradiol increases insulin content and produces mild glucose intolerance after 4 days of treatment, while STX does not alter these parameters after a 6-day treatment." (PMID 22506040, 2012). "Insulin secretory defects are more pronounced in PCOS women having first-degree relatives with T2DM, and appear to develop earlier in the evolution of glucose intolerance in women with PCOS than in the general population." (PMID 21899727, 2011). "The fact that OEA administration was reported to promote glucose intolerance without altering insulin levels suggests that the OT effects on glucose tolerance are independent from OEA synthesis." (PMID 21980491, 2011). "However, in the prediabetic state, insulin fails to regulate blood glucose, leading to impaired blood glucose and glucose intolerance." (PMID 39861423, 2025). "Infection focus as respiratory origin, malignancy, cardiovascular instability, high-dose vasopressor, low cardiac output, poor lactate clearance, and glucose intolerance requiring insulin were significantly more frequent in the non-surviving group than surviving group." (PMID 40394230, 2025). "Notably, global-Sucnr1-knockout mice fed a high-fat diet (HFD) show defective insulin secretion and glucose intolerance, without significant changes in β cell mass, raising suspicion of its role as a regulator of β cell function." (PMID 38713514, 2024).
Glucose intolerance (continued). "However, in contrast to our predictions, male RT-SAKO mice exhibited glucose intolerance at 16–18 weeks, without decreased insulin sensitivity." (PMID 38280449, 2024). "Similar increases in AUC insulin levels were noted during OGTT in individuals with TS on GH/oxandrolone combination therapy in a subsequent study, which also demonstrated a reversibility of glucose intolerance in TS individuals upon discontinuation of these treatments." (PMID 36875465, 2023). "Interestingly, in Spraque Dawley rats, HF diet feeding did not provoke glucose intolerance or an increase in plasma fasted insulin or glucose." (PMID 36678151, 2023). "Compared with the sham group (Sham), the OGF and OGFE groups, in which OVX mice have high levels of FSH, whether with estrogen supplements or not, showed overt glucose intolerance but normal insulin sensitivity." (PMID 37914684, 2023). "We reasoned that the conventional serum insulin measurement may not reflect the changes in β-cell function, given that the Ctnna1ΔEndo/ΔEndo mice exhibit only mild glucose intolerance." (PMID 37610090, 2023). "There was no sufficient variation in insulin sensitivity between control and βKO mice, indicating that the glucose intolerance may not be attributable to insulin resistance." (PMID 37277555, 2023). "Thus, gut exposure to particles in mice on standard diet led to glucose intolerance as a consequence of impaired insulin secretion, rather than insulin resistance." (PMID 36895000, 2023). "Interestingly, in aged animals, clopidogrel did not evoke glucose intolerance nor decreased insulin levels." (PMID 37490001, 2023). "Additionally, mice with haploinsufficiency of Talin-1 and Stat3 genes, but not that of either gene, in β-cells exhibit significant glucose intolerance and reduced insulin expression, suggesting that both factors function in the same genetic pathway." (PMID 37903776, 2023). "However, HF feeding induced glucose intolerance and reduced insulin sensitivity were significantly improved by CD36 peptide treatment as demonstrated by GTT and ITT assays as well as reduced fasting plasma glucose and insulin levels from obese mice." (PMID 37980376, 2023). "The lack of a comparable pattern in pancreatic islets from glucose intolerance patients may be evidence of an impaired miRNA network in insulin function of diabetic patients." (PMID 35408847, 2022). "Similarly, despite the glucose intolerance indicated from an oGTT, we did not identify evidence of the alteration of insulin signaling in LW on the hepatic level." (PMID 35457071, 2022). "Therefore, the consumption of apples before meals does not increase the postprandial blood glucose even if glucose intolerance is induced; rather, it inhibits the absorption of sugar and moderates the secretion of insulin." (PMID 35742001, 2022). "Moreover, mice with lymphocyte deficiency were not protected from short-term high-fat-diet induced glucose intolerance, insulin resistances and accumulation of macrophages in the adipose tissue." (PMID 35955975, 2022). "BMM-sEVs transfer miRNA-212-5p to adjacent β cells dor insulin secretion, downregulating sirtuin 2 (SIRT2) in recipient β cells, impairing the SIRT2-mediated Akt/glycogen synthase kinase-3β (GSK-3β)/β-catenin pathway, finally disrupting insulin secretion and glucose intolerance in islet β cells." (PMID 35832790, 2022). "Lack of GPR92 expression led to glucose intolerance via reduced insulin secretion." (PMID 36066975, 2022). "However, at 26wks of age, male and female βOGAKO mice exhibited glucose intolerance, without gross alterations to insulin tolerance." (PMID 36387851, 2022). "Metabolic data obtained longitudinally after 8 and 16 weeks of either standard or high‐fat diet indicate that eNOS+/− genotype is characterized by progressive glucose intolerance and marked impairment of insulin responsiveness to a glucose load, regardless of the diet regimen." (PMID 35986504, 2022).
Glucose intolerance (continued). "In our study, the lack of insulin secretory response, together with glucose intolerance, in both 1/2Nx and Sham operated rats suggested that improvements induced by 1/2Nx may be independent from insulin signaling in DEK-DM rats." (PMID 34356489, 2021). "The protective effects of maternal DHA supplementation against glucose intolerance in obese animals was accompanied by a decrease in serum insulin levels, suggesting that maternal DHA supplementation might protect the offspring from developing glucose intolerance by increasing insulin sensitivity." (PMID 34578953, 2021). "However, our data do not confirm that the afternoon glucose intolerance is mediated by changes in postprandial insulin response as suggested in studies that did not include exercise." (PMID 34959894, 2021). "Interestingly, central inhibition of GNPDA2 provoked significant glucose intolerance without changes in plasma insulin levels." (PMID 34912841, 2021). "In addition, central administration of the GNPDA2 antagonist, prior to an intraperitoneal glucose tolerance test, resulted in glucose intolerance in comparison to vehicle without altering insulin levels." (PMID 34912841, 2021). "In mouse model, defects in NAD+ biosynthesis impaired glucose-stimulated insulin secretion in pancreatic islets and disrupted glucose homeostasis, while treatment with NMN could increase glucose-stimulated insulin secretion and improve glucose intolerance." (PMID 34366891, 2021). "The absence of differences in insulin secretion between groups, despite a difference of glucose concentration, could represent an early sign of impaired insulin secretion and glucose intolerance." (PMID 31991777, 2020). "However, at 4–5 months of age, we saw no changes in insulin sensitivity, glucose intolerance or energy expenditure in Hmox2-/- mice compared to WT littermates." (PMID 32992485, 2020). "Therefore, this delay in insulin level changes and GLUT4 activation might be an important reason for glucose intolerance in this fish." (PMID 33178047, 2020). "Interestingly, although maternal hypothyroidism altered glucose homeostasis in young adult offspring, differences in insulin sensitivity and glucose intolerance were not significant in older animals (16–18 weeks of age) kept on standard chow." (PMID 32472193, 2020). "Similarly, overexpression of kinase-negative PKCδ in mice protects from HFD-induced glucose intolerance, increases insulin level and pancreatic islets size, and decreases apoptosis marker cleaved caspase-3 in β-cells in comparison to control animals." (PMID 32466765, 2020). "However, it did aggravate glucose intolerance, with non-fasting glucose and serum insulin significantly increased in MG-treated animals." (PMID 32878255, 2020). "The inhibition of GLUT2‐mediated glucose uptake in TMLTg mice was analogous to that in liver‐specific GLUT2 knockout mice, in which animals showed suppressed hepatic glucose uptake but not glucose secretion, resulting in glucose intolerance and insulin insensitivity." (PMID 32440483, 2020). "We show that episodic maternal exposure to psychostimulants during pregnancy coincident with the intrauterine specification of pancreatic β cells permanently impairs their ability of insulin production, leading to glucose intolerance in adult female but not male offspring." (PMID 31750562, 2020). "Therefore, any treatment that normalizes GH/IGF-I should improve insulin sensitivity and decrease glucose intolerance, provided that the treatment does not also decrease insulin secretion as well, as is the case with SSAs." (PMID 30474822, 2019). "Current treatment uses insulin, but no consensus exists on the treatment of glucose intolerance." (PMID 31878961, 2019). "Thus, blocking activation of GPR54 by endogenous kisspeptin during pregnancy induces glucose intolerance by reducing glucose-induced insulin secretion rather than through effects on insulin target tissues." (PMID 31619585, 2019).
Glucose intolerance (continued). "Finally, the authors of these studies observed that there is a consensus in animal model studies that non-action of GH would lead to decreased insulin and glucose levels, glucose intolerance and increased IS despite having a higher percentage of fat." (PMID 31939483, 2019). "For this purpose, we analyzed the immune cell composition in blood, adipose tissue, and liver as well as markers of glucose intolerance and insulin secretion in SPF and non-SPF mice [called “antigen exposed” (AE), here], receiving normal diet (ND) or high-fat diet (HFD)." (PMID 29892281, 2018). "However, hepatic and peripheral insulin clearance in T2DM subjects and the roles of both types of clearance in the changes in temporal pattern of circulating insulin concentration during the progression of glucose intolerance have yet to be examined." (PMID 29560274, 2018). "Therefore, in obese mice, exposure to N10% improved glucose intolerance, in the absence of any discernable improvement in insulin tolerance and under conditions of weight neutrality." (PMID 29507654, 2018). "However, we observed glucose intolerance was significantly improved in female SERT−/− mice without changes in insulin levels and β-cells function, suggesting that pregnancy improves insulin sensitivity in female SERT−/− mice." (PMID 28442777, 2017). "Interestingly, the insulin signalling defects in FAIM-KO mice were not concurrently accompanied by glucose intolerance as showed by the GTT." (PMID 26866272, 2016). "Interestingly, these mice also present mild glucose intolerance with a reduced insulin secretion (data not shown)." (PMID 26901633, 2016). "The absence of insulin secretion defect and glucose intolerance on NJ mice on ND could be related to the use of OGTT in the present study." (PMID 27403868, 2016). "Although the reduced insulin response might be a reason for the elevated glucose levels, it has been reported that the rats with glucose intolerance had no changes in plasma insulin response after sleep disturbance, making this explanation less likely." (PMID 27738407, 2016). "First, although the insulin response might refer to the mechanism of the glucose intolerance, we did not evaluate the insulin levels after IPGTT." (PMID 27738407, 2016). "Indeed, these doses decreased plasma insulin levels and induced glucose intolerance in C57BL/6 and CB1+/+, but not in CB1−/− littermates." (PMID 26563389, 2016). "We found that in control diet–fed mice, CAP exposure led to neither systemic glucose intolerance nor changes in body weight, fasting blood glucose, plasma insulin levels, or the HOMA-IR and HOMA-β scores indicating that the mice were not insulin resistant or glucose intolerant." (PMID 27128347, 2016). "While we did not directly test insulin sensitivity here, our findings suggest improvement of hepatic insulin sensitivity, since absence of Plin2 prevents alcohol-induced glucose intolerance and restores glycogen stores (data not shown) to levels of control-fed WT mice." (PMID 24831094, 2014). "The initial PANDER knockout (PANKO) model was generated on a mixed genetic background and demonstrated glucose intolerance in the presence of enhanced hepatic insulin sensitivity (HIS) with no observed differences in peripheral insulin sensitivity or fasting glycemic levels." (PMID 25217499, 2014). "However, one puzzle is that the insulin resistance in skeletal muscle and liver did not result in glucose intolerance and hyperinsulinaemia in the AS160-knockout mouse." (PMID 23078342, 2013). "The effects of chronic in vivo CB receptor stimulation on insulin release should be investigated and might partly contribute to the observed glucose intolerance, without affecting the glucose-induced insulin levels." (PMID 23393605, 2013). "Furthermore, their mice fed KD for 2 weeks had mild glucose intolerance in the absence of a significant change in insulin sensitivity." (PMID 23874946, 2013).